CRP (C-reactive protein)
Diseases named in the same sentence as CRP in open-access papers (continued):
Sharing a sentence is not in itself a finding about the gene and the disease.
epilepsy (29 papers, 2016 to 2026). A brain disorder characterized by episodes of abnormally increased neuronal discharge resulting in transient episodes of sensory or motor neurological dysfunction, or psychic dysfunction. "Increased levels of C reactive protein have been found to be associated with epilepsy, suggesting a connection between inflammation and seizures." (PMID 39825393, 2025). "Standardized mean differences (SMDs) with 95% confidence intervals (95% CIs) were used as a measure to assess the association between CRP and epilepsy." (PMID 31620066, 2019). "The most pronounced epilepsy-associated differences were decreased levels of eotaxin, IL-1β, C-reactive protein, and vascular cell adhesion molecule (VCAM)-1 and increased IL-12 p70 levels." (PMID 27737716, 2016). "In conclusion, NLR had a superior accuracy to CRP in the epilepsy diagnostic process, especially in SE and IEcs dogs, and might reflect the neuroinflammation involved in epileptogenesis." (PMID 39511714, 2024). "A systematic review and meta-analysis revealed that PD and epilepsy were associated with increased CRP levels; nevertheless, it remains questionable whether CRP serves as a causal risk factor or whether these diseases lead to a response of CRP." (PMID 34386016, 2021). "Baseline inflammatory indices (NLR, SII, CRP) were significantly elevated in patients with drug-resistant epilepsy compared to those with SeLECTS (p < 0.001)." (PMID 42051563, 2026). "Mean leukocyte count (p < 0.001), median neutrophil count (p < 0.001), mean platelet distribution width (PDW) (p = 0.005), and median C-reactive protein (CRP) (p = 0.045) levels were significantly higher in epilepsy patients with comorbidities." (PMID 40507116, 2025). "This meta-analysis aims to evaluate the effect of levetiracetam on serum C-reactive protein (CRP) in children with epilepsy." (PMID 35517802, 2022). "Serum CRP levels are upregulated in childhood epilepsy and reduced by levetiracetam in children with epilepsy." (PMID 35517802, 2022). "The serum CRP level in childhood epilepsy was significantly higher than the healthy controls (pooled standardized mean difference (SMD): 6.930, 95% CI: 2.716-11.143, z = 3.22, p < 0.01)." (PMID 35517802, 2022). "Therefore, we further investigated the levels of serum biomarkers, including SIRT3, IL-6, IL-1β, TNF-α, and CRP in epilepsy patients." (PMID 39091611, 2024). "Despite information about a direct relationship between CRP and EEG being missing, the existing results on the changes of CRP levels in epilepsy suggest that EEG markers could be affected by CRP concentration." (PMID 39685972, 2024). "Furthermore, a meta-analysis correlated increased CRP levels with epilepsy, and elevated hsCRP has been recommended as a biomarker in idiopathic epilepsy." (PMID 37873776, 2023). "Patients with seizures were older, had more commonly an underlying epilepsy and had more frequently altered C-reactive protein than those without seizures." (PMID 36553366, 2022). "A logistic regression model was further constructed for severity that included the following factors: vomiting, epilepsy, CSF CrAg titre, blood culture, C-reactive protein level, ventriculomegaly, CSF fungal burden, multi-site infection, and PC-1 and PC-4 scores." (PMID 36032125, 2022). "Besides, serum CRP level was significantly decreased by the treatment of levetiracetam in childhood epilepsy (pooled SMD: 3.505, 95% CI: 1.638-5.373, z = 3.68, p < 0.01)." (PMID 35517802, 2022). "Notably, our data suggested a better efficiency of P2X7R plasma levels for the diagnosis of epilepsy when compared with the inflammation marker CRP." (PMID 34572093, 2021). "For neurological disease, we found a protective role of CRP on PD and epilepsy." (PMID 34386016, 2021).
epilepsy (continued). "C-reactive protein (CRP) and interleukin-6 (IL-6) levels, which are indicators of oxidative stress and inflammation, play an important role in the evaluation of the effects on cardiac health as a result of carbamazepine administration in male rats used as epilepsy models." (PMID 41295638, 2025). "However, while a significant association between CRP levels and epilepsy has been observed in some studies, this was not confirmed by others in line with our results." (PMID 34572093, 2021). "Therefore, our aim was to evaluate both the CRP activity and NLR in epileptic dogs with respect to the etiology and type of seizure and to uncover if the NLR might be used as a diagnostic marker in differentiating the main types of epilepsy." (PMID 39330787, 2024). "Compared to the healthy volunteers, epilepsy patients had significantly increased serum levels of the inflammatory factors IL-6, IL-1β, TNF-α, and CRP (P < 0.05), while SIRT3 levels were significantly decreased." (PMID 39091611, 2024). "In this paper, we have investigated both the CRP activity and NLR in dogs with epilepsy with respect to etiology and symptomatology." (PMID 39330787, 2024). "Patients with prevalent epilepsy also had a higher CRP level compared with those with incident epilepsy or non-epilepsy (median CRP [IQR], 2.21 [0.81, 5.97] vs. 1.89 [1.14, 5.81] vs. 2.57 [0.51, 5.63], p = 0.036)." (PMID 40563626, 2025). "Experimental results demonstrated that CRP concentration and EEG activity are affected in epilepsy." (PMID 39685972, 2024). "Because the P2X7R has been shown to be an important driver of inflammation and because peripheral inflammation is one of the hallmarks of epilepsy, we next sought to establish whether P2X7R plasma levels correlate with the inflammation marker CRP." (PMID 34572093, 2021). "Vascular mediators CRP, ICAM-1, and VCAM-1 all showed epilepsy-related differences." (PMID 27737716, 2016). "Non-specific inflammatory indicators such as C-reactive protein (CRP) and erythrocyte sedimentation rate (ESR) may also be elevated in some epilepsy patients, particularly those with systemic infections or autoimmune comorbidities." (PMID 41306289, 2025).
Erythema (29 papers, 2014 to 2026). Redness of the skin, caused by hyperemia of the capillaries in the lower layers of the skin. "At the time of last evaluation, tests, including C-reactive protein and fecal calprotectin, were within normal limits, complete colonoscopy revealed erythema, edema, mucosal friability, loss of vascular patterns, and pseudo-polyps." (PMID 34559136, 2021). "Using fever, erythema, elevated CRP, and eosinopenia in diagnostic screening, our positivity rate was 90.9%." (PMID 29968555, 2018). "In our case, although our patient had mildly elevated ESR and CRP, dermatology was confident in the clinical diagnosis of erythema ab igne." (PMID 40443590, 2025). "The manifestation of pain, swelling, and erythema in affected tissues can be attributed to the production of CRP and elevation in ESR levels, commonly observed in the context of chronic diseases or autoimmune disorders." (PMID 38522056, 2024). "In this study, an RRP model was built by combining independent predictive factors, including fever, periungual erythema, elevated CRP, anti-MDA5 antibody, and anti-Ro52 antibody." (PMID 34646845, 2021). "The most common AEs were development of erythema in the site of injection (38 cases), C-reactive protein increase (five cases), blood creatine phosphokinase increase (four) and red-blood-cell sedimentation-rate increase (two)." (PMID 31683812, 2019). "In accordance with our criteria for THA re-implantation, none of these patients presented any preoperative clinical or laboratory signs of infection persistence (erythema, calor, persistent pain or elevated serum CRP) prior to second-stage surgery." (PMID 30013895, 2018). "Based on these results, we consider fever, erythema, elevated CRP, and eosinopenia to be good markers of JSF, even when there is no eschar present." (PMID 29968555, 2018). "However, an abnormally high level of CRP more than 50 mg/L, a positive wound culture, and clinical signs such as erythema and swelling indicate a wound infection which should prompt treatment with antibiotics." (PMID 25374597, 2014). "Around 1 month postoperatively, the patient showed inflammatory signs due to chest erythema as well as fever, WBC count 8600/μL, and CRP 4.46 mg/dL." (PMID 35520291, 2022). "However, excluding patients in the early postoperative period is due to the early clinical swelling and erythema and also the high false positivity rate of ESR and CRP values." (PMID 41049961, 2025). "Analyzed factors included mechanic's hands (yes vs. no), skin ulceration (yes vs. no), periungual erythema (yes vs. no), fever (yes vs. no), anti-MDA5 antibody (positive vs. negative), anti-Ro-52 antibody (positive vs. negative), and elevated CRP (yes vs. no)." (PMID 34646845, 2021).
hyperthyroidism (29 papers, 2010 to 2024). Overactivity of the thyroid gland resulting in overproduction of thyroid hormone and increased metabolic rate. "Those with possible infection (including statements in medical records, fever ≥ 38 °C, CRP ≥ 10 mg/L or positive blood culture) during treatment or with hypo-/hyperthyroidism were excluded." (PMID 35966581, 2022). "On the Acute period of disease; extremely high acute phase reactants such as ESR and CRP is usually seen together with a subclinical hyperthyroidism." (PMID 32063967, 2020). "The level of C reactive protein (CRP) is also elevated and laboratory markers of hyperthyroidism are often present but the blood concentration of thyroid antibodies is normal in most patients." (PMID 30728805, 2019). "Clinical improvement was noted with a decrease in CRP but also an accentuation of hyperthyroidism after five days, which then gradually subsided." (PMID 31791298, 2019). "Here, we measured plasma CRP as a control biomarker of inflammation to evaluate whether changes in plasma ET-1 are specific for AF secondary to hyperthyroidism." (PMID 30513109, 2018). "Ferritin was increased, while transferrin and CRP were reduced during hyperthyroidism." (PMID 26866603, 2016). "However, the impact of hyperthyroidism on CRP is still controversial." (PMID 24367378, 2013). "The C reactive protein (CRP) level is also elevated and laboratory markers of hyperthyroidism are often present, but the level of thyroid antibodies is normal in most patients." (PMID 32079059, 2020). "In contrast, hyperthyroidism results in rapid metabolic activity, which may lead to the hyperactivity of adrenergic nervous system, stimulation of immune system and significantly increased peripheral blood flow: all those conditions might result in an increase of CRP concentration." (PMID 24794233, 2014). "In this study, we provide, for the first time, data on the association between several novel surrogate cardiovascular markers (hs-CRP, fibrinogen, homocysteine, and PAI-1) and CA-IMT in patients with clinical/subclinical hypo- and hyperthyroidism." (PMID 22505888, 2012). "At univariate linear regression, higher ESR values correlated with thyrotoxicosis severity (significantly for T4, p = 0.035; with a trend towards significance for T3, p = 0.07), whereas CRP did not correlate with hyperthyroidism severity." (PMID 35094372, 2022). "It is interesting to point out that CRP was unchanged from the euthyroid state to subclinical hyperthyroidism, which suggests that this increase in Lp(a) was not related with inflammation-based changes." (PMID 32300332, 2020).
myocardial ischemia (29 papers, 2009 to 2025). A disorder of cardiac function caused by insufficient blood flow to the muscle tissue of the heart. "Conclusion: a high level of CRP was associated with the presence and extent of stress-induced myocardial ischemia in MPI." (PMID 38398769, 2024). "Further analysis concluded that high-sensitivity CRP (hs-CRP) levels are directly proportional to cardiovascular risk and the magnitude of the inflammatory response to myocardial ischemia." (PMID 39274304, 2024). "Some studies suggest that a pronouncedincrease in leukocyte and CRP levels due to the inflammatory response caused bycardiopulmonary bypass and myocardial ischemia could be considered as predictivefactors for the occurrence of AF." (PMID 39077087, 2023). "CRP is a marker of the inflammatory response that is highly expressed in the endothelial cells of patients with myocardial ischemia." (PMID 40427511, 2025). "Spectral perfusion screening has been reported to have lower CRP levels in patients with normal myocardial functions than with myocardial ischemia." (PMID 33094574, 2020). "Some researchers have shown that sulodexide can preserve coronary vascular glycocalyx and attenuate myocardial ischemia/reperfusion injury and the deposition of CRP." (PMID 29207649, 2017). "We then assessed the mean plasma levels of C-reactive protein and myocardial ischemia markers (troponin I, CK-MB, and myoglobin) according to the PON1 55 carriers." (PMID 22536511, 2012). "Finally, the SSS of the third patient (C) was 15, SRS 5, and SDS 10 (severe myocardial ischemia, with good reversibility—green arrows), and CRP was 11 mg/L." (PMID 38398769, 2024). "CRP levels increased up to 24–48 h after myocardial ischemia reperfusion injury." (PMID 36551811, 2022). "As already known, our study determined the relationship between CRP and myocardial ischemia." (PMID 33094574, 2020). "Therefore, low CRP levels can improve myocardial ischemia management." (PMID 40427511, 2025). "Consequently, a rather high CRP/troponin ratio, signifying high specificity, was selected as threshold for the diagnosis of myopericarditis in order to obtain a value beyond which the probability of active cardiac ischemia would be low." (PMID 33886564, 2021). "Macrophage inflammatory protein-1 alpha (MIP-1α) and C-reactive protein (CRP) are pro- inflammatory biomarkers that quantify clinical and subclinical inflammation in cardiac ischemia in cardiac inflammation and disease." (PMID 38433948, 2024). "CRP is a non-specific acute-phase glycoprotein produced by the liver in response to trauma, myocardial ischemia and infections." (PMID 36836679, 2023). "In conclusion, silent myocardial ischemia and myocardial fibrosis are common in APS, independent of APS-related and classic CVD risk factors, hs-CRP and hs-TnT levels or coronary angiography findings." (PMID 31340567, 2019). "We hypothesise that the increase in values of IL-6, hs-CRP and their correlation to leptin in AMI patients could be due to participation of leptin in the signaling cascade after myocardial ischemia." (PMID 22891684, 2012). "Rosmarinic acid has been shown to protect against inflammation and myocardial cell apoptosis during myocardial ischemia/reperfusion injury by activating peroxisome proliferator-activated receptor γ and inhibiting the production of inflammatory cytokines, such as IL-6, TNF-α, and C-reactive protein." (PMID 34484404, 2021). "Finally, total cholesterol, LDL cholesterol, HDL cholesterol, triglyceride and high-sensitive C-reactive protein (hs-CRP) concentrations were not significantly different or associated with carotid arterial disease, PAD, or myocardial ischemia, respectively." (PMID 21838881, 2011).
oral cancer (29 papers, 2010 to 2025). "Grimmet al.19 were able to identify a large number of total leukocytes, neutrophils, and high levels of CRP, and also they indicated that a small number of lymphocytes is associated with a lower survival rate in oral cancer." (PMID 37224312, 2023). "In summary, even if a number of factors are associated with the CRP/alb ratio in oral cancer patients, only the comorbidity combination of age and disease history and heavy alcohol use increased the CRP/alb ratio in OSCC patients independently." (PMID 33740951, 2021). "According to the results, prediagnostic concentrations of CRP are associated with subsequent development of oral cancer and suggest that plasma CRP level is a potential marker of increased risk of cancer." (PMID 30842796, 2018). "The findings were in accordance with the results of a study conducted by Kumar and Bhateja who showed that prediagnostic concentrations of CRP in precancerous patients are strongly associated with subsequent development of oral cancer." (PMID 30842796, 2018). "The findings imply that plasma CRP levels may be a potential indicator of elevated cancer risk and that pre-diagnostic CRP concentrations are linked to the later development of oral cancer." (PMID 38910781, 2024). "However, consistent associations have been demonstrated between CRP and oral cancer risk in Asian population." (PMID 38071306, 2023). "Indeed, in addition to predicting early mortality, CRP/alb appears to be promising for predicting the risk of postoperative infections in oral cancer patients." (PMID 33740951, 2021). "In addition, a Taiwanese group published various studies on the prognostic role of CRP in oral cancer and could consistently demonstrate an association between elevated CRP levels and survival." (PMID 32182693, 2020). "Post hoc tests showed that the salivary CRP levels were significantly higher in the oral cancer and OPMD groups than in the controls." (PMID 39851610, 2025). "The mean calculated salivary CRP level detected in the oral cancer group was 4.21 ng/mL (SD = 7.05, median = 1.20, interquartile range = 0.36–4.19)." (PMID 39851610, 2025). "Evidence suggests that mean CRP levels are higher in patients with OPMDs and oral cancer at advanced tumor stages." (PMID 39851610, 2025). "Background/Objectives: The present study aimed to test the efficacy of the chair-side rapid salivary C-reactive protein assay kit in differentiating oral potentially malignant disorders (OPMDs) and oral cancer from normal mucosa using whole salivary samples." (PMID 39851610, 2025). "CRP is an early marker for inflammation, and it was seen that the preoperative serum CRP level effect was more prominent in oral cancer and was a prognosticator in OSCC." (PMID 36362963, 2022). "In this field, inflammation-related proteins including cytokines and C-reactive protein (CRP) and proteases such as matrix metalloproteinases (MMPs) have recently been proposed as potential salivary biomarkers for oral cancer." (PMID 36005828, 2022). "Another study of patients with oral cancer reported that current and former betel nut users had significantly higher levels of high-sensitivity CRP." (PMID 35267993, 2022). "CRP production increases as a response to these stimuli mediators and has been shown worsen inflammatory status and advance progression of the oral cancer." (PMID 33740951, 2021). "Elevated CRP levels have been reported to be associated with a lower rate of DFS and OS in operable oral cancers." (PMID 33482792, 2021). "In this multivariate survival analysis on patients with oral cancer, high CRP/ neutrophil was shown to predict worse overall survival (HR: 2.7 95% CI 0.68–10.75 p = 0.16)." (PMID 29196718, 2017). "The presence of an elevated serum CRP level preoperatively (≥5.0 mg/L) is an important prognostic indicator in oral cancer in the Taiwanese population." (PMID 28209200, 2017).